SLC34A3 (solute carrier family 34 member 3)
Description:
Involved in actively transporting phosphate into cells via Na(+) cotransport in the renal brush border membrane. The cotransport has a Na(+):Pi stoichiometry of 2:1 and is electroneutral (By similarity).
Synonyms: NaPi-2c; NPT2C; NPTIIC; FLJ38680; HHRH
Tractability: Antibody: its Gene Ontology location is reachable by antibodies, with high confidence; UniProt places it where antibodies can reach, with medium confidence; UniProt predicts a signal peptide or a membrane-spanning region. PROTAC: a small molecule that binds it is known.
Target class: Transporter; SLC34 family of sodium phosphate co-transporters; Electrochemical transporter; SLC superfamily of solute carriers
Gene: Protein-coding gene on chromosome 9 (137,230,757 to 137,236,555, forward strand). Ensembl gene ENSG00000198569.
Subcellular location: Apical cell membrane
Pathways (Reactome):
Disease: Defective SLC34A3 causes Hereditary hypophosphatemic rickets with hypercalciuria (HHRH)
Transport of small molecules: Type II Na+/Pi cotransporters
Gene Ontology:
Molecular function: protein binding; sodium:phosphate symporter activity
Biological process: intracellular phosphate ion homeostasis; phosphate ion transport; sodium ion transport; phosphate ion transmembrane transport; sodium-dependent phosphate transport; sodium ion transmembrane transport
Cellular component: apical plasma membrane; brush border; brush border membrane; plasma membrane; vesicle; membrane
Genetic constraint (gnomAD): Loss-of-function variants: 61 observed, 42.48 expected, observed/expected ratio (o/e) 1.44, 90% interval 1.17 to 1.77. The synonymous counts are far from expectation, so gnomAD's model fits this gene poorly and the ratio says little. Missense variants: 969 observed, 790.39 expected, observed/expected ratio (o/e) 1.23, 90% interval 1.16 to 1.29. Synonymous variants: 451 observed, 371.04 expected, observed/expected ratio (o/e) 1.22, 90% interval 1.12 to 1.31.
Homologues: Orthologues: chimpanzee SLC34A3 (98% identical), macaque SLC34A3 (95% identical), dog SLC34A3 (81% identical), mouse Slc34a3 (80% identical), rat Slc34a3 (79% identical), guinea pig SLC34A3 (72% identical), pig SLC34A3 (65% identical), tropical clawed frog slc34a3 (57% identical), Caenorhabditis elegans ZK563.2 (29% identical). Paralogues in human: SLC34A2 (51% identical), SLC34A1 (49% identical).